FAM120B (family with sequence similarity 120 member B)
Description:
Functions as a transactivator of PPARG and ESR1. Functions in adipogenesis through PPARG activation (By similarity).
Synonyms: PGCC1; CCPG; KIAA1838; SAN1; dJ894D12.1
Tractability: PROTAC: ubiquitination databases record sites on it; its protein half-life has been measured.
Gene: Protein-coding gene on chromosome 6 (170,290,703 to 170,407,067, forward strand). Ensembl gene ENSG00000112584.
Subcellular location: Nucleus
Subcellular location (Human Protein Atlas): Nucleoplasm; Cytosol
Pathways (Reactome):
Developmental Biology: Transcriptional regulation of white adipocyte differentiation
Metabolism: PPARA activates gene expression
Gene Ontology:
Molecular function: protein binding
Biological process: fat cell differentiation; peroxisome proliferator activated receptor signaling pathway
Cellular component: nucleus
Genetic constraint (gnomAD): Loss-of-function variants: 75 observed, 91.17 expected, observed/expected ratio (o/e) 0.82, 90% interval 0.68 to 1. The upper end of that interval is the gene's LOEUF score, 1, which puts it in group 4 of 6, group 1 being the genes least tolerant of losing a copy. Missense variants: 1,002 observed, 1,126.7 expected, observed/expected ratio (o/e) 0.89, 90% interval 0.84 to 0.94. Synonymous variants: 400 observed, 413.49 expected, observed/expected ratio (o/e) 0.97, 90% interval 0.89 to 1.05.
Homologues: Orthologues: chimpanzee FAM120B (94% identical), macaque FAM120B (92% identical), dog FAM120B (72% identical), rabbit FAM120B (71% identical), mouse Fam120b (70% identical), guinea pig FAM120B (68% identical), rat Fam120b (68% identical), pig FAM120B (65% identical), tropical clawed frog fam120b (35% identical), zebrafish fam120b (26% identical). Paralogues in human: FAM120A (21% identical), FAM120C (21% identical).
Diseases named in the same sentence as FAM120B in open-access papers:
FAM120B is named in the same sentence as 3 diseases in open-access papers, as found by Europe PMC text mining. Sharing a sentence is not in itself a finding about the gene and the disease. The quoted sentences say what the papers report.
Fanconi anemia (1 paper, 2018). Fanconi anemia (FA) is a hereditary DNA repair disorder characterized by progressive pancytopenia with bone marrow failure, variable congenital malformations and predisposition to develop hematological or solid tumors. "Here the authors identify FAM120B/SAN1, a 5′ exonuclease involved in the repair process of Interstrand Crosslinks independently of the Fanconi Anemia pathway." (PMID 29968717, 2018).
FAM120B also shares sentences with these, for which no sentence is quoted: rheumatoid arthritis (1 paper); tumor (1).